GDAP1L1 (ganglioside induced differentiation associated protein 1 like 1)
Synonyms: dJ881L22.1; dJ995J12.1.1
Tractability: PROTAC: its protein half-life has been measured.
Gene: Protein-coding gene on chromosome 20 (44,247,099 to 44,280,947, forward strand). Ensembl gene ENSG00000124194.
Subcellular location (Human Protein Atlas): Endoplasmic reticulum
Gene Ontology:
Cellular component: mitochondrion
Genetic constraint (gnomAD): Loss-of-function variants: 20 observed, 32.92 expected, observed/expected ratio (o/e) 0.61, 90% interval 0.43 to 0.88. The upper end of that interval is the gene's LOEUF score, 0.88, which puts it in group 3 of 6, group 1 being the genes least tolerant of losing a copy. Missense variants: 359 observed, 479.76 expected, observed/expected ratio (o/e) 0.75, 90% interval 0.69 to 0.82. Synonymous variants: 192 observed, 204.51 expected, observed/expected ratio (o/e) 0.94, 90% interval 0.83 to 1.06.
Homologues: Orthologues: chimpanzee GDAP1L1 (100% identical), guinea pig GDAP1L1 (98% identical), mouse Gdap1l1 (98% identical), dog GDAP1L1 (98% identical), pig GDAP1L1 (97% identical), rabbit GDAP1L1 (97% identical), rat Gdap1l1 (95% identical), macaque GDAP1L1 (87% identical), tropical clawed frog gdap1l1 (81% identical), zebrafish gdap1l1 (79% identical), Drosophila melanogaster GstE11 (14% identical), Drosophila melanogaster GstE12 (14% identical), and 29 more. Paralogues in human: GDAP1 (53% identical), EEF1G (15% identical), GSTT2B (14% identical), GSTT2 (14% identical), CLIC4 (13% identical), CLIC5 (12% identical), GSTT4 (12% identical), CLIC6 (11% identical), CLIC1 (11% identical), CLIC3 (11% identical), CLIC2 (10% identical), GSTZ1 (9% identical), and 2 more.
Diseases named in the same sentence as GDAP1L1 in open-access papers:
GDAP1L1 is named in the same sentence as 6 diseases in open-access papers, as found by Europe PMC text mining. Sharing a sentence is not in itself a finding about the gene and the disease. The quoted sentences say what the papers report.
psoriasis (2 papers, 2021). An autoimmune condition characterized by red, well-delineated plaques with silvery scales that are usually on the extensor surfaces and scalp. "We aimed to explore the possible molecular signaling of the GDAP1L1/Drp1 axis involved in activated macrophages in psoriasis." (PMID 34638757, 2021). "The identification of GDAP1L1/Drp1 as the pivotal factors in psoriasis’ pathogenesis can help develop therapeutic strategies targeting mitochondrial dynamics." (PMID 34638757, 2021). "Further study is needed to yield detailed insight into the molecular pathways that mediate GDAP1L1/Drp1 translocation in psoriasis." (PMID 34054833, 2021). "Administration of shGDAP1L1-expressed THP1 in mice remarkably alleviated psoriasis-like symptoms, suggesting the connection of GDAP1L1 in lesional development." (PMID 34638757, 2021). "Moreover, the GDAP1L1 depletion remarkably suppressed macrophage infiltration and psoriasiform symptoms, supporting its crucial role in psoriasis development and maintenance." (PMID 34638757, 2021). "Whether the GDAP1L1/Drp1 axis is also crucial in clinical psoriasis requires further justification." (PMID 34638757, 2021). "However, there are very few investigations about the role of fission or GDAP1L1 on psoriasis." (PMID 34638757, 2021).
glioma (1 paper, 2021). A benign or malignant brain and spinal cord tumor that arises from glial cells (astrocytes, oligodendrocytes, ependymal cells). "However, no research has been reported on GDAP1L1 in glioma." (PMID 34650972, 2021).
Globozoospermia (1 paper, 2015). Any structural anomaly of the acrosome resulting in a round sperm head. "Six imprinted genes showed different 5hmC patterns between normal and abnormal sperm (GDAP1L1, GNAS, KCNK9, LIN28B, RB1, RTL1), and five imprinted genes showed different 5hmC patterns between normal and globozoospermia sperm (KCNK9, LIN28B, RB1, SLC22A18, ZDBF2)." (PMID 25762640, 2015).
myocardial infarction (1 paper, 2025). Gross necrosis of the myocardium, as a result of interruption of the blood supply to the area, as in coronary thrombosis. "Previous studies indicate that miR-150 mitigates adverse remodeling and fibrosis following myocardial infarction by targeting pro-fibrotic genes such as Hoxa4 and apoptosis-related genes like Gdap1l1, thereby improving cardiac function." (PMID 41300398, 2025).
neuromuscular disease (1 paper, 2017). "Mutations in a similar human gene (GDAP1) cause Charcot-Marie-Tooth type 4A, and this plus the result with mouse Gdap1l1 suggests that human GDAP1L1 is a candidate for neuromuscular disease." (PMID 28190221, 2017).
GDAP1L1 also shares sentences with these, for which no sentence is quoted: tumour (1 paper).